NLGN3 (neuroligin 3)
Diseases named in the same sentence as NLGN3 in open-access papers (continued):
Sharing a sentence is not in itself a finding about the gene and the disease.
autism (continued). "Other variants (SNVs and CNVs) in NLGN1 and/or other family members NLGN3 and NLGN4 were previously associated with suicide, PTSD, autism, obsessive–compulsive disorder (OCD), and depression." (PMID 36319817, 2022). "Neuroligin 3 (NLGN3) and neurexins (NRXNs) constitute a canonical transsynaptic cell-adhesion pair, which has been implicated in autism." (PMID 33758193, 2021). "Our study is only preliminary basic research, and further functional analysis of novel mutations in the neuroligin pathway will provide a better understanding of the involvement of the NLGN3 gene in autism in the Indian population." (PMID 35012288, 2021). "The representative NLGNs, NLGN3 and NLGN4, are essential for cell adhesion and synaptogenesis, and thus, deletion of the NLGN3 gene shows the same phenomenon as autism." (PMID 32244359, 2020). "Here, we studied characteristics of microglia and astrocytes in the Neuroligin-3 (NL3R451C) mouse model of autism since these cell types are involved in regulating both immune and synapse function." (PMID 32879325, 2020). "Genetic defects in neuroligin 3 (NL3), a member of the NL protein family, are associated with autism." (PMID 31849609, 2019). "Foldy and colleagues employ previously characterized mouse models of Nlgn3R451C knock-in (KI) and Nlgn3 KO, which have both demonstrated autism-related phenotypes." (PMID 30854511, 2017). "Mutations of NLGN3 and NLGN4 in particular are associated with X-linked intellectual disability, seizures, and autism behaviors." (PMID 28880200, 2017). "In 2003, a mutation in neuroligin 3 (NLGN3; p.R451C) and a mutation in neuroligin 4X (NLGN4X; p.D396 fs) were reported in two unrelated Swedish autism families." (PMID 28948087, 2017). "Here, we provide an overview of the current evidence of changes to eCB signaling in experimental models of autism, specifically pertaining to the neuregulin 3 (Nlgn3) and Fragile X (FXS) mouse models." (PMID 30854511, 2017). "Here, we performed a case-control study to assess the association between noncoding genetic variants in NLGN3 and NLGN4X genes and autism, in an Italian cohort of 202 autistic children analyzed by high-resolution melting." (PMID 27782075, 2016). "Surprisingly, our data suggested that deletion of Neuroligin-3 in D1R+ MSNs of the mature nucleus accumbens was sufficient to generate the behavioral phenotypes seen in two separate Neuroligin-3 autism models." (PMID 26903795, 2016). "In support of the notion that cerebellar pathology and glutamatergic dysregulation co-occur, in a mouse model of fragile X, neuroligin-3 KO mice were found to exhibit deficits in social behaviors analogous to those seen in autism." (PMID 23717269, 2013). "A point mutation (R451C) that replaces an arginine with a cysteine in the extracellular portion of neuroligin-3 was identified in two brothers, one with severe autism and the other with Asperger syndrome." (PMID 21826280, 2011). "Despite the association of numerous synaptic gene mutations with ASD, the presence of behavioral abnormalities in mice expressing autism-associated R617W mutation in synaptic adhesion protein neuroligin-3 (NL3) has not been established." (PMID 40071366, 2025). "Despite these limitations, the enhanced role of autism-related NLGN3 R451C mutant astroglia suggests a significant pathological contribution of astroglia to the development of autism spectrum disorder (ASD), indicating potential targets for future ASD treatments." (PMID 39775628, 2025). "NLGN3 is one such high‐confidence candidate gene for autism." (PMID 40816723, 2025). "Taken together, these findings suggest that neuroligin-3 plays a role in regulating enteric nervous system-mediated GI physiology and that changes to Nlgn3 mRNA expression could contribute to GI dysfunction in the Nlgn3R451C mouse model of autism." (PMID 37509099, 2023). "The autism-associated R451C mutation reduces Nlgn3 mRNA expression in cholinergic but not in VIPergic submucosal neurons." (PMID 37509099, 2023).
autism (continued). "Additional evidence strongly suggests that mutations in NLGN3 and NLGN4 are involved in autism." (PMID 37790478, 2023). "The alterations in neuronal circuits in autism may be reversible by re-expression of NLGN3, as an NLGN3-knockout mice model of non-syndromic autism showed impaired heterosynaptic competition and altered mGluR-dependent synaptic plasticity." (PMID 35296811, 2022). "In the present study, we recorded the prevalence of autism in the North Karnataka region of India for the first time, investigated the genetic profile of neuroligin 3 gene in the Indian autistic population by DNA sequencing, and reported novel molecular-level changes." (PMID 35012288, 2021). "At neuronal level, the autism-related Nlgn3 R451C mutation causes selective impairment in the non-canonical pathway." (PMID 33758193, 2021). "It has been reported in the literatures that multiple neurodevelopmental-related susceptibility genes might be associated with the risk of autism, such as neuregulin genes NRX1/3, NLGN3/4, etc.." (PMID 33716803, 2021). "Given the common genetic association of the R451C substitution and NLGN3 deletion with ASD, it is possible that disrupted EC signaling could contribute to autism pathophysiology in these mouse models." (PMID 28880200, 2017). "Together, data suggested that mutations on NLGN3 and NLGN4X might increase the risk of autism while polymorphisms of different nucleotides in autism still need further investigation." (PMID 27992373, 2017). "Alteration of NLGN3 contributes to the induction of autism-related behaviors." (PMID 27184741, 2016). "The involvement of neuroligins in ASD has been firstly confirmed in two Swedish families by a de novo missense mutation (R451C) in NLGN3 and a frameshift mutation (1186insT) in NLGN4X causing premature protein termination (D396X), respectively associated with typical autism and Asperger’s syndrome." (PMID 27782075, 2016). "Together with mouse studies of neuroligin-3 and Fragile X mental retardation 1 and a valproate rat model of autism, our work brings to eight the number of autism rodent models with alterations in cerebellum-dependent function." (PMID 26158416, 2015). "Interestingly, other autism candidate genes, including NLGN3, NRXN1, RELN, and GABAA, were also included in the predicted gene network, thus supporting the investigation of our selected genes as ASD-relevant transcriptional targets of RORA." (PMID 23697635, 2013). "Siblings with ASDs had mutations in the neuroligins NLGN3 and NLGN4, the two X-linked genes, which impact synapse-localized cell adhesion molecules, indicating synaptogenesis breakdown may be a risk factor for autism." (PMID 41245836, 2025). "Studies in NLGN3 R451C knock-in mice and human neurons have demonstrated notable gain-of-function changes, which may contribute to autism-associated phenotypes." (PMID 39775628, 2025). "However, mutations of NLGN3 and NLGN4 are encountered in a small fraction of autism cases." (PMID 35296811, 2022). "As the involvement of inhibitory transmission in autism-related synapse pruning was unclear in the previous studies, the cerebellum of NLGN3-R451C mutant mice provides a good model to examine whether and how inhibitory transmission contributes to developmental synapse elimination in ASD." (PMID 34262438, 2021). "Our results suggest that a balance between the canonical and non-canonical NLGN3 pathways may contribute to the development of sociality, with the autism-related R451C mutation disrupting this balance to diminish the non-canonical PTPδ–NLGN3 pathway." (PMID 33758193, 2021).
autism (continued). "However, an independent study of 107 autism patients (102 males, 5 females) found no genetic variants for both X-linked genes NLGN3 and NLGN4X in ASD on a high functioning level by screening four polymorphisms and one novel synonymous variant." (PMID 27992373, 2017). "Interestingly, one missense mutation causing R451C substitution within a highly conserved region of the extracellular esterase-homology domain of the Nlgn3 gene was detected in two male siblings, one with autism, severe intellectual disabilities and seizures and the other with Asperger syndrome." (PMID 23761734, 2013). "Many mutations in genes encoding neurexins (including hemizygous CNV deletions and missense mutations) and neuroligins (e.g., R451C for NLGN3 and a frameshift insertion mutation for NLGN4) have been associated with ASD, intellectual disability, and schizophrenia." (PMID 23935565, 2013). "Hence, NLGN3 may be a candidate gene for the male predominance of autism." (PMID 35012288, 2021). "We sequenced the NLGN3 and NLGN4X loci in a sample of 144 male individuals with a diagnosis of autism; all the patient samples were obtained from the multiplex AGRE repository." (PMID 23020841, 2012). "Coding sequence variations in NLGN3 and NLGN4 are rare, but contribute to the aetiology of autism." (PMID 35012288, 2021). "Here, we examined the effects of mutants of the autism-related gene neuroligin 3 (nlg3) on fly social and non-social behaviors." (PMID 32610435, 2020). "It has been reported that a mouse expressing R451C NLGN3 as an endogenous protein exhibits social behavioural traits typical of autism, along with neurotransmission alterations, not observed in the NLGN3-knockout mice." (PMID 26621873, 2016). "Interestingly enough, some other mouse models of autism were negative in the three chamber test as Nlgn3 knock-in mouse and Fmr1." (PMID 28448442, 2017). "Lastly, the network state space framework has been applied to study alterations in the organization of hippocampal oscillations in mice lacking neuroligin 3 (NLG3 KO; neuroligin-3 knock out), an animal model of autism." (PMID 37462671, 2023). "Consistent with NLGN3 R451C KI, NLGN3KO mice display behavioral phenotypes relevant to autism; including reduced ultrasonic vocalizations, a lack of social novelty preference, and a decrease in total brain volume." (PMID 27047540, 2016).
glioma (106 papers, 2015 to 2026). A benign or malignant brain and spinal cord tumor that arises from glial cells (astrocytes, oligodendrocytes, ependymal cells). "Neuron-glioma synapses and activity-dependent release of neuroligin-3 are implicated in promoting tumor proliferation and invasiveness." (PMID 41514565, 2025). "For instance, DAB2IP deficiency was found to upregulate Wnt‐mediated NLGN3 secretion, which in turn transformed neighboring glioma cells into cancer stem cells (CSCs) and contributed to tumor aggressiveness." (PMID 40589077, 2025). "NLGN3 expression is associated with decreased survival in patients with glioma, again suggesting a role between activity-dependent signaling and aggressive tumor behavior." (PMID 36614191, 2023). "In support of this, the action of activity-dependent growth signals such as neuroligin-3 (NLGN-3) has been found to cause the expression of synaptic genes in human glioma cells." (PMID 36614191, 2023). "A soluble form of neuroligin-3, a synaptic protein, was able to activate PI3K-mTOR in high-grade glioma, and increased neuroligin-3 expression was negatively associated with patient survival." (PMID 37554158, 2023). "On an expression level, NLGN-3-associated PI3K-mTOR signaling in glioma cells led to an upregulation of synapse-associated genes." (PMID 36357661, 2022). "Our recent report shows that NLGN3 levels are associated with postoperative recurrence of gliomas 5, western blotting analysis of NLGN3 showed that the level of NLGN3 was higher in the PTBE region compared to normal brain tissue." (PMID 33754006, 2021). "Having established that PIEZO1 is a primary actuator responsible for NLGN3-mediated shedding of CSPG4, we hypothesized that blocking the PIEZO1 response in glioma would mimic loss of microenvironmental NLGN3 and affect glioma growth in vivo." (PMID 40791371, 2025). "However, seminal preclinical work has shown a prominent role for neuronal activity in glioma growth: mediated by neuroligin-3 (NLGN3), increased neuronal activity causes faster glioma growth." (PMID 30094719, 2018). "Conversely, this could be the result of some sort of inverted U-shape in the association between global oscillatory activity and NLGN3 expression, or of a particular subtype of glioma in this group." (PMID 30094719, 2018). "Furthermore high NLGN3 expression is associated with glioma recurrence." (PMID 34373757, 2021). "Furthermore, we explored the underlying mechanism of NLGN3 in glioma cell lines." (PMID 34485271, 2021). "Patients with neuroligin-3-positive high-grade and isocitrate dehydrogenase (IDH)-wild type glioma have a decreased risk of memory and attention and executive functioning deficits, again not modified by epilepsy." (PMID 42291752, 2026). "Neuroligin-3 is a postsynaptic activity-dependent protein, considered a key component of brain-glioma interactions, specifically at neurogliomal synapses." (PMID 42291752, 2026). "Certainly, active neurons have been shown to promote high-grade glioma proliferation and growth by means of secreting mitogens, such as the synaptic protein neuroligin-3 (NLGN3), a leading candidate mitogen." (PMID 40806177, 2025). "In summary, the findings presented here underscore a critical role for NLGN3 in the interplay between neuronal activity and glioma progression, unveiling a newly appreciated mechanistic pathway by which gliomas exploit neuronal signals for growth." (PMID 40791371, 2025). "Taken together, these observations highlight the therapeutic potential of disrupting NLGN3 shedding or downstream effects on glioma cells." (PMID 40791371, 2025). "Key to these interactions is the role of neuroligin-3 (NLGN3), a synaptic adhesion molecule shed in response to neuronal activity that functions as a paracrine factor crucial for glioma growth." (PMID 40791371, 2025).
glioma (continued). "Literature data reported that neurons support glioma progression by upregulating neuroligin-3 (NLGN3), which induces a phosphoinositide-3-kinase (PI3K) signaling-mediated proliferative activity in glioma cells." (PMID 40143161, 2025). "The effects of serotonergic neurons on glioma cells are mediated by both known (e.g. NLGN3) and previously underappreciated growth factors such as ICAM-1 and NCAM-1, and through activation of the serotonin receptor HTR2A." (PMID 41427306, 2025). "NLGN3 promotes glioma cell proliferation by activating multiple oncogenic signaling pathways, including PI3K-mTOR, SRC, and RAS, offering a novel perspective on the integration of gliomas with neural circuits." (PMID 40092993, 2025). "The unexpected dependency of DMG and other high-grade gliomas on NLGN3 in the tumor microenvironment prompted a deeper exploration into the effects of NLGN3 on glioma cell states." (PMID 41460355, 2025). "Here, we aim to address these questions to elucidate the mechanism of NLGN3 signaling to OPCs and glioma cells." (PMID 40791371, 2025). "In agreement with prior studies, we found that NLGN3 exposure increased proliferation of glioma cells." (PMID 40791371, 2025). "Here, we elucidate the mechanistic pathway whereby shed NLGN3 interacts with glioma and their normal glial counterpart." (PMID 40791371, 2025). "As postsynaptic regulators of synaptic plasticity, s-NLGN3 critically mediates neuromodulation in gliomas by binding to glioma cell membranes." (PMID 41018101, 2025). "Neurons also release the growth factor neuroligin-3 (NLGN3), which facilitates glioma cell proliferation through the PI3K-mTOR signaling pathway." (PMID 40426960, 2025). "Unexpectedly, P13K upregulates NLGN-3 gene expression in glioma cells, generating more sNLGN-3 in the glioma microenvironment." (PMID 41018101, 2025). "In gliomas, NLGN3 is a powerful mitogen that activates PI3K–mTORC1, facilitates synaptic reorganization, and speeds electrical incorporation of tumor cells into neural networks." (PMID 41463339, 2025). "Neuronal activity has been observed to promote high-grade glioma proliferation through upregulation of neuroligin-3 (NLGN3)." (PMID 40310890, 2025). "Currently, research is scarce, and concrete evidence is lacking regarding the specific effects of the interaction between NLGN3 and glioma by the NF ‐κB pathway, further research is warranted to elucidate these mechanisms." (PMID 39469896, 2024). "Once released, soluble NLGN3 (sNLGN3) diffuses to glioma cells and binds surface receptors, inducing the FAK-PI3K-mTOR signaling pathway that results in glioma cell proliferation." (PMID 38473812, 2024). "NLGN3 released by neurons in response to activity stimulates glioma cell proliferation and induces the expression of synapse-related genes in glioma cells." (PMID 39201639, 2024). "In glioma, NLGN3 is cleaved from synaptic neurons and OPCs in an activity-dependent fashion by the ADAM10 metalloproteinase." (PMID 38473812, 2024). "This cleavage transforms NLGN3 into its secretory form (sNLGN3), which subsequently acts on glioma cells within the TME to promote tumor progression." (PMID 39469896, 2024). "This neuronal activity can trigger the shedding of the synaptic protein Neuroligin-3 (NLGN3), which activates oncogenic signaling cascades and drives synaptic gene expression in glioma cells, potentially contributing to epileptic activity." (PMID 39201639, 2024). "Healthy neurons near the glioma, known as peritumoral neurons, can be tricked into supporting glioma growth by releasing factors, like neuroligin-3 (NLGN3)." (PMID 39202716, 2024). "The latest findings further suggest a correlation between neuronal secretion of NLGN3 and the severity of gliomas." (PMID 39469896, 2024). "Emerging studies have illuminated that NLGN3 acts on glioma cells accompanied by activation of the extracellular regulated protein kinases (ERK) pathway and nuclear factor kappa‐B (NF‐κB) pathway." (PMID 39469896, 2024).